PRC1 (protein regulator of cytokinesis 1)
Diseases named in the same sentence as PRC1 in open-access papers (continued):
Sharing a sentence is not in itself a finding about the gene and the disease.
lung adenocarcinoma (continued). "PRC1, TNS4, and CDKN3, which were used to construct the model, had significantly higher mRNA expression in lung adenocarcinoma samples than normal samples in the TCGA cohort." (PMID 40697537, 2025). "Zhang and collaborators (2021) have identified seven N6-methyladenosine-related immune prognostic genes (i.e., PSMD10P1, DIDO1, ABCA5, CIITA, PRC1, ZWILCH, and ANLN) for lung adenocarcinoma (LUAD)." (PMID 37189849, 2023). "The intersections of LPS induction-related genes, lung adenocarcinoma differential genes, and univariate cox genes were obtained, and five genes (TNS4, PRC1, MKI67, CDKN3, BIRC5) were obtained, which were defined as the characteristic genes associated with LPS induction." (PMID 40697537, 2025). "PRC1 was reported to involve in Wnt/β-catenin signaling pathway and then promote cancer proliferation and tumorigenesis in kinds of cancers, such as HCC and lung adenocarcinoma." (PMID 31043166, 2019). "Moreover, reduced expression of PRC1 suppresses the proliferation and invasion of lung adenocarcinoma cells in vitro and in vivo by inducing G2/M phase cell cycle arrest and apoptosis, suggesting that PRC1 may serve as an oncogene and potential therapeutic biomarker for lung adenocarcinoma." (PMID 28646916, 2017). "When stratified by various histological types, the patients with increased PRC1 mRNA expression had lower overall survival (OS) rates with NSCLC and lung adenocarcinoma, but not with lung squamous carcinoma." (PMID 28646916, 2017). "Patients with high PRC-1 mRNA expression had a worse OS and PFS among NSCLC and lung adenocarcinoma but not in lung squamous carcinoma." (PMID 28646916, 2017).
pancreatic cancer (9 papers, 2016 to 2025). "This study aimed to assess the clinical relevance of PRC1 in pancreatic cancer and its impact on cancer cell characteristics." (PMID 39409930, 2024). "Based on data from The Cancer Genome Atlas (TCGA) and a cell-based assay, PRC1 has emerged as a clinical marker for pancreatic cancer." (PMID 39409930, 2024). "To assess PRC1 expression in pancreatic cancer tissues and cells, we analyzed data from the HPA database using IHC." (PMID 39409930, 2024). "To assess the clinical relevance of PRC1 in pancreatic cancer, we analyzed data from TCGA focusing on gene expression and survival rates." (PMID 39409930, 2024). "To investigate the functional role of PRC1 in pancreatic cancer, we knocked down PRC1 to assess cell viability and proliferation in both KPC and PanC02 cell lines." (PMID 39409930, 2024). "Our study has shown the significant differential expression of PRC1 in pancreatic cancer stages and its correlation with immune cell infiltration and other markers of pancreatic cancer." (PMID 39409930, 2024). "We examined the relationship between PRC1 expression and immune cell infiltration in pancreatic cancer using the TIMER database." (PMID 39409930, 2024). "For example, ANLN and PRC1 were mutated in cells derived from a malignant melanoma, and RANBP2, TTK, PP2R1A, and CEP192 were mutated in cells from pancreatic cancers." (PMID 27144335, 2016). "Therefore, further studies are necessary to evaluate the PRC1-mediated pathway with other key factors in pancreatic cancer." (PMID 39409930, 2024). "Therefore, targeting PRC1 can be a promising strategy to enhance the efficacy of chemotherapy in pancreatic cancer patients." (PMID 39409930, 2024). "Moreover, previous studies have indicated that PRC1 lacks clear clinical value in pancreatic cancer." (PMID 39409930, 2024). "In this study, we investigated PRC1 as an anticancer drug candidate for pancreatic cancer." (PMID 39409930, 2024). "Furthermore, we found that reducing PRC1 expression effectively inhibits the proliferation and recovery of pancreatic cancer cells." (PMID 39409930, 2024). "We investigated the correlation between PRC1 and these markers in pancreatic cancer." (PMID 39409930, 2024). "Our study suggests that PRC1 could serve as a pancreatic cancer biomarker and a potential drug target." (PMID 39409930, 2024). "We assessed apoptosis in these cells to determine whether inhibiting PRC1 can enhance the sensitivity of pancreatic cancer cells to Doxo." (PMID 39409930, 2024). "Therefore, our study suggests that PRC1 is one of the potential drug targets for pancreatic cancer, and we expect that blocking PRC1 will improve combination therapy with immunotherapeutics." (PMID 39409930, 2024). "PRC1 was overexpressed in pancreatic cancer and negatively correlated with CD4+ T cells." (PMID 39409930, 2024). "Our research reveals a crucial link between PRC1 and the development of pancreatic cancer." (PMID 39409930, 2024). "So, our study suggests that PRC1 is a promising therapeutic target for pancreatic cancer." (PMID 39409930, 2024). "Therefore, targeting PRC1 may enhance the efficacy of immunotherapy in pancreatic cancer by modifying the immune landscape of the tumor." (PMID 39409930, 2024). "Additionally, PRC1 showed a positive correlation with established pancreatic cancer markers." (PMID 39409930, 2024). "In this report, we discovered that KDM2B, a member of variant PRC1 complex and also a histone H3 demethylase, epigenetically regulated the downregulation of several epithelial marker genes including CDH1, which was indispensable for TGF-β-induced EMT of lung and pancreatic cancer cells." (PMID 33779563, 2021). "PRC1 expression was markedly higher in pancreatic cancer patients compared to the cohort without cancer (p = 0.0001)." (PMID 39409930, 2024). "Additionally, PRC1 expression was lower in WT839, a normal pancreas cell line from wild-type C57BL/6 mice, compared to pancreatic cancer cell lines KPC and PanC02." (PMID 39409930, 2024).
pancreatic cancer (continued). "However, the role of PRC1 in “cold tumors”, such as pancreatic cancer, has not been fully studied." (PMID 39409930, 2024).
bladder cancer (8 papers, 2015 to 2023). "MicroRNA-139-5p, a mesenchymal stem cell-derived exosome, can promote bladder cancer cell apoptosis by silencing polycomb repressive complex 1 (PRC1) in bladder cancer, thereby inhibiting tumor cell proliferation and migration." (PMID 36936418, 2023). "An in vitro study showed that knockdown of PRC1 by using siRNA significantly inhibited the proliferation of breast and bladder cancer cells." (PMID 28646916, 2017). "In summary, our present data support a possible model of bladder cancer progression through an epigenetic mechanism of coordinated deregulation of the PRC1 and PRC2, and the miR-200 family." (PMID 26517683, 2015). "PRC1 plays an important role in the carcinogenesis of bladder cancer." (PMID 35387129, 2022). "Results showed that deletion of PRC1 inhibited bladder cancer cells’ ability to proliferate and spread, as well as halted the induction of EMT, which was shown by changes in the production of E-cadherin, and Bax and decreases in the synthesis of N-cadherin, Vimentin, SNAIL, Bcl-2, and PCNA." (PMID 36684446, 2022). "Additionally, PRC1’s role as a carcinogen in bladder cancer cells has been confirmed." (PMID 36684446, 2022).
colorectal cancer (8 papers, 2014 to 2025). A primary or metastatic malignant neoplasm that affects the colon or rectum. "The PRC1 has also been identified as one of the hub macrophage‐related genes in colorectal cancer patients." (PMID 37647439, 2023). "Bmi1, member of the PRC1, has also been found to be a candidate target gene of miR-203, where ectopic expression of miR-203 in pancreatic and colorectal cancer cells induced apoptosis and repressed cell growth." (PMID 25004126, 2014). "Recent studies have shown that overexpression of PRC1 may promote the formation of various tumors, including ovarian cancer and colorectal cancer." (PMID 34120619, 2021). "Both Dnmt1 and Dnmt3b interact with the polycomb group repression complexes (PRC1 and PRC2), and regulate distinct sites in colorectal cancer development." (PMID 26808831, 2016).
gastric cancer (8 papers, 2010 to 2023). A primary or metastatic malignant neoplasm involving the stomach. "Overexpression of PRC1 in gastric cancers was associated with poor disease‐specific survival and overall survival." (PMID 28190297, 2017). "Further analysis revealed that MSI gastric cancers are enriched for the intestinal histological variant; thus, further study is warranted to investigate why PRC1 mRNA level is elevated in intestinal type of gastric cancer." (PMID 28190297, 2017). "In this study, we verified that PRC1 is significantly overexpressed in gastric cancers and that its overexpression is strongly associated with poor prognosis of patients." (PMID 28190297, 2017). "We found that CBX7, a constituent of the polycomb repressive complex 1 (PRC1), plays an important role in maintaining stem cell-like characteristics of gastric cancer cells via the activation of AKT pathway and the downregulation of p16." (PMID 29422082, 2018). "To generalize our finding, we recapitulated PRC1 gene expression from the large cohorts of gastric cancer patients that are available from the GEO database (accession numbers GSE63089, GSE27342 and GSE65801) and data are given as scatterplots." (PMID 28190297, 2017). "Together, these data suggested a role of PRC1 in the motility and invasiveness of gastric cancer cells." (PMID 28190297, 2017). "Our data should contribute to a better understanding of the molecular mechanism of gastric carcinogenesis and indicate that PRC1 is a promising molecular target for gastric cancer treatment." (PMID 28190297, 2017). "Consistently, PRC1 gene expression was significantly up‐regulated in all three different gastric cancer cohorts." (PMID 28190297, 2017). "Statistical analysis revealed that gastric cancer tissues expressed a significantly higher level of PRC1 protein than adjacent non‐tumoural tissues." (PMID 28190297, 2017). "Collectively, these data indicate that PRC1 is essential for gastric cancer cell proliferation both in vitro and in vivo." (PMID 28190297, 2017). "We then compared the PRC1 expression level between different subtypes of gastric cancer by analysing the TGGA cohort." (PMID 28190297, 2017). "Immunohistochemistry was then performed to assess the PRC1 protein expression in tissue microarrays containing 133 formalin‐fixed, paraffin‐embedded gastric carcinomas." (PMID 28190297, 2017). "We first determined and compared PRC1 mRNA expression of 17 pairs of samples from patients who underwent resection of primary gastric carcinoma using qRT‐PCR." (PMID 28190297, 2017). "MRNA level of PRC1 gene is markedly increased in gastric carcinomas relative to the paired adjacent non‐tumour tissues." (PMID 28190297, 2017). "To date, however, the impact of PRC1 expression on gastric carcinoma patient survival and its potential oncogenic role and molecular mechanisms in gastric carcinoma has not been elucidated." (PMID 28190297, 2017). "Western blotting showed that up‐regulation of PRC1 protein was detected in 7 of 13 (53.8%) randomly selected gastric carcinomas." (PMID 28190297, 2017). "In this study, we studied PRC1 expression status and its clinical significance in gastric carcinoma." (PMID 28190297, 2017). "Both in vitro and in vivo functional assays were performed to characterize the biological effects of PRC1 in gastric carcinoma." (PMID 28190297, 2017). "In the present study, we found that upregulating the expression of PRC1 component Cbx7 in gastric cancer cell lines MGC803 and BGC823 led to significantly suppress the expression of genes within the p16-Arf-p15 locus." (PMID 21060834, 2010).
gastric cancer (continued). "We propose that abnormal PcG expression results in an altered composition of the PRC1 in gastric cancer cells, which probably affects expression of target genes involved in regulation of senescence and/or the cell cycle." (PMID 21059209, 2010). "We next examined whether PRC1 is required for the tumorigenic phenotypes of gastric cancer cells by silencing PRC1 expression with short hairpin RNA." (PMID 28190297, 2017). "We further demonstrated that PRC1 is essential for the survival of gastric cancer cells." (PMID 28190297, 2017). "We finally confirmed that PRC1 is a novel downstream target of piperlongumine in gastric cancer." (PMID 28190297, 2017). "Next, we investigated the effect of PRC1 depletion on migratory capacity of gastric cancer cells." (PMID 28190297, 2017). "Our findings shown in this study suggest that PRC1 might play critical roles in tumour cell growth and be a promising target for the development of novel anticancer drugs to gastric carcinoma." (PMID 28190297, 2017). "BMI1, the core of PRC1, which ubiquitinates lysine 119 at histone H2A (H2AK119ub1), is highly expressed in gastric cancer (GC), colon cancer (CRC), and breast cancer." (PMID 37220590, 2023). "PRC1 might serve as a prognostic biomarker and potential therapeutic target for gastric carcinoma." (PMID 28190297, 2017). "The introduction of shRNA into the gastric cancer cell lines AGS and HGC27 dramatically decreased the expression level of PRC1 relative to control cells expressing scrambled control shRNA." (PMID 28190297, 2017). "Furthermore, p27 and GADD45α, which inhibits cell‐cycle progression from G2 to M phase in gastric cancer cells 24, 29, were remarkably increased in AGS cells but not HGC27 cells when PRC1 was depleted." (PMID 28190297, 2017).
leukemia (7 papers, 2014 to 2024). A malignant (clonal) hematologic disorder, involving hematopoietic stem cells and characterized by the presence of primitive or atypical myeloid or lymphoid cells in the bone marrow and the blood. "Conversely, the loss of PRC1 activity induces the differentiation of leukemia cells through its enzymatic actions on H2AK119ub." (PMID 39048945, 2024). "When one of the subunits of PRC1, Cbx7, is overexpressed in hematopoietic and progenitor cells, it promotes leukemia." (PMID 39048945, 2024). "Overexpression of Cbx7, one of the PRC1 subunit, in hematopoietic and progenitor cells promoted leukemia." (PMID 31700696, 2019). "Several groups have investigated the functional requirement of these PRC1 components in MLLr leukemia." (PMID 28232907, 2017). "Cancer-exome-sequencing endeavours have recently revealed that core components of the KDM2B/PRC1 complex, including KDM2B itself and BCOR/L1, are frequently mutated in a range of cancers, particularly leukemias." (PMID 24856970, 2014). "Furthermore, we have shown that the exchange activity of Vav3 found in the nucleus is important for the proliferation and progression of p190-BCR-ABL+ leukemia using a PRC1- and to a lesser extent PRC2-dependent mechanism." (PMID 35650206, 2022). "Furthermore, it is suggested that USP3 may counteract the effects of the PRC1 complex, potentially promoting leukemia cell differentiation, including in cases of leukemia, by removing the H2AK119ub modification." (PMID 39048945, 2024). "Importantly, RB-3 treatment drastically reduced the global level of ubiquitination of H2A and induced differentiation of leukemia cell lines, implying that inhibitors of PRC1 might be used to carry out the treatment of leukemia." (PMID 36076977, 2022). "Therefore, USP3 may counteract to PRC1 complex to regulate cancer development including leukemia via removal H2AK119ub." (PMID 31700696, 2019). "CBX function in MLLr leukemia appears to be independent of its role in PRC1, however, and instead involve the recruitment of the histone acetyl transferase Tip60 to fusion target loci." (PMID 28232907, 2017).
ovarian carcinoma (7 papers, 2020 to 2024). A malignant neoplasm originating from the surface ovarian epithelium. "PRC1 gene knockdown can reduce the proliferation, metastasis, and multidrug resistance of ovarian cancer cells." (PMID 35387129, 2022). "This investigation highlighted CCNA2, TRIP13, CDK1, CDC20 and PRC1 as viable targets for our structure-based drug discovery campaign, as they all had a crystallised structure available in the Protein Data Bank, strong evidence of a role in ovarian cancer and known inhibitors." (PMID 39184376, 2024).